STIM1 (stromal interaction molecule 1)
Diseases named in the same sentence as STIM1 in open-access papers (continued):
Sharing a sentence is not in itself a finding about the gene and the disease.
breast carcinoma (continued). "Thirdly, the native SOCE pathway was found to be mediated by Orai3 in estrogen receptor-positive breast cancer cells whereas the canonical STIM1/Orai1 pathway was shown to be used by estrogen receptor-negative breast cancer cells." (PMID 24797725, 2014). "Blocking SOCE, by a pharmacological inhibitor SKF96365 or by siRNA-mediated silencing of STIM1 or Orai1, impaired the focal adhesion turnover and invasive migrations of breast cancer cells." (PMID 23594099, 2013). "Our results demonstrated that PMCA2, ORAI-1, and STIM1 were differentially expressed in the presence of Lr EV stimulation, suggesting a potential role for bacterial EVs in influencing the differentiation, migration, and metastasis of breast cancer cells." (PMID 40491474, 2025). "Knockdown of STIM1 via RNA interference decreases tumor metastasis in breast cancer." (PMID 40491474, 2025). "SOCE is co-regulated by ORAI1 and STIM1 and is strictly required for breast cancer cell migration." (PMID 36677874, 2023). "Using glycosylation-deficient STIM1 and Orai1 mutants we have found SOCE in breast cancer cells is insensitive to N-linked glycosylation of these proteins, a mechanism that might be relevant to evade apoptosis." (PMID 36612199, 2022). "For example, STIM1 was originally isolated as a tumor suppressor and was validated as such in an independent screen, yet in the context of several cancers including breast cancer STIM1 and Orai1 are crucial for metastasis." (PMID 34069353, 2021). "It remains so far elusive whether a co-expression of STIM1, Orai1 and SK3 in HEK 293 cells or overexpression of STIM1 in breast cancer cells alters the interplay of the Orai1/SK3 channel complex." (PMID 33333945, 2020). "Moreover, knockdown of ORAI1 or STIM1 in breast cancer cells led to reductions in in vitro migration and invasion and in vivo metastasis." (PMID 33569087, 2020). "Higher STIM-1 expression is correlated with migration, tumour size and clinical outcome in cervical cancer and such correlation with tumour size is also seen in breast cancer." (PMID 32098295, 2020). "Downregulation of STIM1 expression by miR-223 resulted in the inhibition of breast cancer invasion." (PMID 33348924, 2020). "Interestingly, the expression of the Stim1 gene is diminished in breast cancer and is practically comparable to normal tissue levels at all stages." (PMID 33511135, 2020). "Since STIM1 promotes cell migration in lung cancer, breast cancer, and melanoma by regulating focal adhesion turnover 14-17, we speculated that it might also be upregulated in metastatic HCC." (PMID 32483465, 2020). "Interestingly, also STIM1-independent Orai1 activation mechanisms have been detected in breast cancer cells." (PMID 33333945, 2020). "Interestingly, in analogy to SK3, SPCA2 has been reported to induce constitutive Ca2+ entry via Orai1 in breast cancer cells in a STIM1-independent manner." (PMID 33333945, 2020). "This suggests that the STIM1/STIM2 expression ratio may represent a good prognostic marker for breast cancer." (PMID 32825277, 2020). "Clinically, STIM1 and Ago2 expression levels do not correlate with breast cancer progression, however in the basal subtype high STIM1 expression is associated with poorer survival." (PMID 31506588, 2019). "A microarray study of breast tumor revealed that the high STIM1/STIM2 expression profiles accompanied by augmented SOCE were correlated with the breast cancer subtype with the poorest prognosis, suggesting the clinical significance of STIM1/STIM2 ratio in breast cancer." (PMID 31252656, 2019). "STIM1 and Orai1 have been shown to be required for breast cancer metastasis in xenograft models." (PMID 31506588, 2019). "A dysregulated STIM1/Orai1/SOC axis is implicated in many pathological conditions such as SCID (severe combined immune deficiency syndrome); cardiovascular and pulmonary diseases; and cancer of the breast, colon, and, esophagus." (PMID 31226817, 2019).
breast carcinoma (continued). "We were first interested in assessing whether STIM1 expression is regulated as the post-transcriptional level in breast cancer cell lines." (PMID 31506588, 2019). "Therefore, in the aggressive basal-like subtype higher STIM1 correlates with decreased survival, arguing for STIM1 expression as an important modulator of breast cancer progression." (PMID 31506588, 2019). "Although both STIM1 and STIM2 sense calcium release, leading to influx of extracellular calcium, our results demonstrate that gain or loss of STIM1 alone has minimal effect on EMT, whereas gain or loss of STIM2 has a substantial impact on EMT in breast cancer cells." (PMID 31464639, 2019). "Interestingly, an analysis of a microarray from McAndrew and colleagues revealed a significantly poorer prognosis for breast cancer patients with a STIM1-high and STIM2-low phenotype." (PMID 30935064, 2019). "STIM1 has a tumor growth promoting role in patients with breast cancer and cervical cancer." (PMID 29783744, 2018). "In vitro studies have reported that SOCE inhibition leads to MDA-MB-231 breast cancer cells with slower focal adhesion turnover rates, which indicates that Ca2+ influx through STIM1 and Orai1 is essential for focal adhesion assembly and disassembly in breast cancer cells." (PMID 30558192, 2018). "In addition to Orai1, its close paralogue, Orai3, has been shown to mediate Stim1-triggered SOCE in oestrogen receptor positive (ER+) breast cancer and non-small cell lung adenocarcinoma cell lines." (PMID 30123430, 2018). "Inhibition of STIM1-mediated Ca2+ entry, by a pharmacological inhibitor SKF96365 or by siRNA-mediated silencing of STIM1 or Orai1, caused the impairment of the focal adhesion turnover and invasive migrations of breast cancer cells." (PMID 28912430, 2017). "Furthermore, our studies also provide a new approach to inhibit breast cancer cell proliferation with small molecules targeting STIM1 and SOCE." (PMID 26919241, 2016). "Furthermore, STIM1 or Orai1 was found to be over expressed in tumor tissues when compared with pre-cancerous tissues in breast cancer patients." (PMID 27199756, 2016). "Orai1 and STIM1 were reported to promote cell proliferation, migration, invasion and apoptotic resistance in breast cancer, glioblastoma, prostate cancer, hepatocellular carcinoma, esophageal squamous cell carcinoma (ESCC) and clear cell renal cell carcinoma (ccRCC)." (PMID 25481035, 2015). "For example, STIM1 was reported to promote cell proliferation and migration, to favor the development of angiogenesis in cervical cancer, and to enhance focal adhesion turnover in breast cancer cells." (PMID 24797725, 2014). "Consistent with the pro-migratory role of STIM1 and Orai1, suppressed expression levels of STIM1 and Orai1 in highly metastatic breast cancer cells inhibited lung metastasis after tail vein injection in immunodeficient SCID mice, which can be mimicked by pharmacological inhibitor SKF96365." (PMID 23594099, 2013). "Hence, targeting the ORAI1/STIM1 function in basal breast cancer cells could lead to a decrease in overall inflammatory signals through its effect on IL6 and PTGS2 expression." (PMID 35682546, 2022). "However, the clinical relevance of STIM1 in breast cancer is still unclear." (PMID 33348924, 2020). "Similarly, SOCE could be reduced with knockdown of ORAI1 or STIM1 in breast cancer cells, but which also led to reductions in in vitro migration and invasion and in vivo metastasis." (PMID 33569087, 2020). "However, the molecular mechanism for the STIM1 regulation of cancer progression remains unclear, especially in the proliferation of breast cancer cells." (PMID 26919241, 2016). "The scenario becomes even more complicated when considering that Orai3 is activated by Stim1 upon intracellular store depletion in some oestrogen receptor-positive breast cancer lines, and that Orai1 may assemble into a supramolecular ternary complex with Stim1 and TRPC1." (PMID 25126575, 2014).
breast carcinoma (continued). "The results from immunofluorescent staining and surface biotinylation in breast cancer cells showed that SPCA2 is partially localized to the plasma membrane where it interacts with the N-terminus of SOC channel Orai1 to elicit the constitutive STIM1-independent Ca2+ influx." (PMID 23594099, 2013). "To understand the molecular mechanism underlying this phenomenon, we measured the mRNA expression of PMCA2 and other calcium channels STIM1, ORAI-1 because of their roles in calcium homeostasis and breast cancer survival and progression." (PMID 40491474, 2025). "Deletion of STIM1 and STIM2, either individually or together, in the isogenic lung derivative and highly metastatic breast cancer cell line LM2-4 revealed that the observed phenomena were not unique to MDA-MB-231 cells." (PMID 40719699, 2025). "In the case of other tumours that remain under the control of oestrogen, such as mammary tumours, SPCA can cooperate with Orai1 to activate STIM1-independent calcium entry, which promotes breast tumorigenesis." (PMID 41226294, 2025). "Further studies on breast cancer cells revealed SPCA2 overexpression in the plasma membrane, where it directly activates Orai1 independently of STIM1." (PMID 41226294, 2025). "E-Syt1 and E-Syt2 are required for full activation of SOCE in ER+ breast cancer MCF7 cells and the TNBC cell lines MDA-MB-231 and BT20, most likely by supporting the close apposition of Orai1 and STIM1 in ER–PM junctions." (PMID 39061158, 2024). "One of the early studies shows that Orai1 and STIM1, which mediate extracellular calcium influx into ER via store‐operated calcium entry (SOCE), were critical for breast cancer cell metastasis." (PMID 36453019, 2023). "This can be achieved by future studies utilizing techniques including siRNA to perform a specific knockdown of STIM1 and STIM2, which will enable researchers to identify the specific roles of these proteins in the TLR4-induced signaling of breast cancer cells." (PMID 37371732, 2023). "Although the focus of our research was to investigate the influence of SOCE on the LPS-mediated signaling in breast cancer cells, we also examined the effect of LPS on the expression of the SOCE-related genes STIM1 and STIM2." (PMID 37371732, 2023). "In ER+ breast cancer cells, SOCE is mediated exclusively by Orai3 and STIM1/STIM2, whereas in ER- breast cancer cells, the canonical CRAC channel consists of STIM1/Orai1, which is sufficient to trigger SOCE." (PMID 36612099, 2022). "In the breast cancer cell line, MCF-7, a novel STIM1-independent mechanism for triggering Ca2+ entry through Orai1 activation via the accessory protein Secretory Pathway Ca2+-ATPase 2 (SPCA2) has been identified." (PMID 36612099, 2022). "In contrast to STIM1 and Orai1, Orai3 has no N-glycosylation consensus motifs; therefore, we have focused our studies in the functional role of STIM1 and Orai1 glycosylation in SOCE in the breast cancer cell types as compared to MCF10A breast epithelial cells." (PMID 36612199, 2022). "EMT and enhancement of cell migration and invasion, along with the differential effects of STIM1 on TGFβ-induced EMT, appear to be correlated with elevated Ca2+ influx via SOCE, as shown in breast cancer cells." (PMID 36556285, 2022). "Diminishing SOCE via STIM1 inhibited the proliferation of cervical cancer, glioblastoma (U251), osteosarcoma (143B and U2OS), lung carcinoma (A549 and SK-MES-1), and breast cancer (MCF7)." (PMID 34572262, 2021). "Consistently, overexpression of STIM1 and STIM2 in the less aggressive MCF-7 breast cancer cells enhances cell migration and invasiveness." (PMID 34069353, 2021). "From the functional point of view, SOCE in MCF7 is mediated by STIM1, STIM2, and Orai3, in contrast to other breast cancer subtypes, such as TNBC cells, where SOCE is entirely dependent on STIM1 and Orai1." (PMID 34439314, 2021).
breast carcinoma (continued). "STIM1-mediated SOCE contributes to cell migration in various tumors, including breast cancer, gastric cancer, colorectal cancer, and melanoma, by modulating focal adhesion turnover and myosin II contraction 14-17." (PMID 32483465, 2020). "Both STIM1 and ORA11 express highly in breast cancer cells and their high expression are correlated with tumor aggressiveness and poor prognosis of breast cancers." (PMID 32211326, 2020). "In breast cancer cells, the interplay of SK3 and Orai1 has been demonstrated to lead to constitutive Orai-dependent, but STIM1-independent Ca2+ entry." (PMID 33333945, 2020). "For example, in breast cancer, glioblastoma, renal cell carcinoma, and esophageal squamous cell carcinoma (ESCC), STIM1 and Orai1 are reported to contribute to proliferation, migration, or both." (PMID 32575848, 2020). "Expression of Orai1 was elevated in MDA-MB-231 cells, while the luminal breast cancer cell type MCF7 exhibited high expression of Orai1 and Orai3 and low expression of STIM1 compared with MCF10A." (PMID 32392840, 2020). "It has been demonstrated that SOCE in estrogen receptor (ER)-positive breast cancer cells is mediated by Orai3 and STIM2/STIM1, whereas SOCE in ER-negative breast cancer cells mostly depends on the canonical Orai1/STIM1 pathway." (PMID 31252656, 2019). "Davis and coworkers have reported that STIM1 and Orai1-mediated SOCE is involved in EMT of breast cancer cells, an essential step in cancer metastasis." (PMID 30558192, 2018). "Altered expression of STIM1 and Orai1, key molecular components of store operated calcium entry (SOCE) pathways have been reported in cervical cancer, breast cancer, and esophageal cancer." (PMID 29861863, 2018). "The process of migration and invasion are an important step in the metastasis of breast cancer, and these processes can be regulated by a variety of factors such as BRMS1, E-cadherin, CXCL12, MMP9, Orai1, Stim1, TGF-β, and VEGF." (PMID 29316690, 2018). "Previous study demonstrated that Stim1 and/or Orai1 mediated FBS-induced Ca2+ signals in the highly aggressive MDA-MB-231 human breast cancer cell line and in the WM793 human melanoma cell line, thereby promoting tumor cell migration." (PMID 30123430, 2018). "Although progress has been made in defining the role of SOCE in cancer progression, the role of STIM1 and SOCE in breast cancer cell proliferation remains poorly understood, especially in the TGF-β-induced suppression of cell proliferation." (PMID 26919241, 2016). "In MDA-MB-468 breast cancer cells, SOCE is involved in EGF-induced epithelial-mesenchymal transition, and EGF-mediated cell growth requires Orai1 and STIM1 in ARPE-19 cells." (PMID 26919241, 2016). "STIM1 and STIM2 are critical regulators of breast cancer cell migration." (PMID 40719699, 2025). "To evaluate whether canonical SOCE components including the Orai1, STIM1, and SARAF proteins, are correlated with breast cancer metastatic potential, we consulted The Cancer Genome Atlas Program (TCGA) NIH database using the GEPIA platform." (PMID 36982380, 2023). "Hence, we have further explored the possible effect of tunicamycin on Orai1 and STIM1 protein expression in MCF10A cells and MDA-MB-231 breast cancer cells." (PMID 36612199, 2022). "Since stromal interaction molecule 1 (STIM1) regulates SOCE channels and influences tumor angiogenesis in cervical and breast cancer, we wondered whether EBV might act via STIM1-dependent Ca2+ signaling to promote tumor angiogenesis in NPC." (PMID 34684224, 2021). "STIM1 is a very relevant component of the Ca2+ entry in non-electrical excitable cells, including breast cancer cells." (PMID 33076541, 2020). "Moreover, microarray analysis data show that, the basal-breast cancer, a breast cancer subtype with a very dismal prognosis, is correlated with an altered relationship between the ORAI1 activators STIM1 and STIM2, characterized by high STIM1/STIM2 ratios." (PMID 32733237, 2020).
breast carcinoma (continued). "The canonical STIM1/Orai1-mediated SOCE mechanism has been found to be required for cell migration of several cancer types, including breast cancer, cervical cancer, gastric cancer, colorectal cancer, hepatocellular carcinoma, renal cell carcinoma, nasopharyngeal carcinoma, glioma, and melanoma." (PMID 31252656, 2019). "Surprisingly, unlike a previous report, we found that STIM1 does not promote EMT in breast cancer cells." (PMID 31464639, 2019). "We show that STIM1 expression is regulated post-transcriptionally by the miRNA machinery and identify miR-223 and miR-150 as regulators of STIM1 expression in the luminal non-aggressive MCF7 breast cancer cell line." (PMID 31506588, 2019). "Our findings suggest that STIM1 and STIM2 differentially regulate intracellular Ca2+ via different downstream signaling pathways and indicate that STIM2 plays an important but previously unappreciated role in promoting breast cancer metastasis." (PMID 31464639, 2019). "In summary, our findings show that Ago2 downregulation could be an effective strategy to upregulate STIM1 expression as observed in MDA-MB-231 cells, suggesting it as one potential mechanism to control STIM1 expression during breast cancer development." (PMID 31506588, 2019). "Other studies in breast cancer and neuroblastoma cells have also highlighted a SOCE defect when MCU was silenced, and the requirement for mitochondrial Ca2+ uptake to ensure IP3-induced STIM1 oligomerization in HeLa cells." (PMID 28495532, 2018). "Motiani and coworkers confirmed that SOCE in triple negative MDA-MB-231 breast cancer cells is entirely dependent on STIM1 and Orai1, while in MCF7, SOCE is mediated by STIM1, STIM2 and Orai3 (overexpressed in this cell line), thus reporting important phenotypic differences between both cell lines." (PMID 30558192, 2018). "Similarly, ER+ breast cancer cell lines show either a normal (HCC 1500 or ZR751) or reduced (MCF7, T47D and BT474) expression of STIM1." (PMID 30558192, 2018). "To examine whether STIM1 and Orai1 are important molecular components involved in high salt mediated inflammatory responses, we used RNA interference (RNAi) to knock down STIM1 and Orai1 in MCF-7 and MDA-MB-231 human breast cancer cells." (PMID 29861863, 2018). "Invadopodia were detected in 90~100% of breast cancer MDA-MB-231 cells and 80~90% of osteosarcoma U2OS cells, whereas suppressed STIM1 expression by two STIM1-specific siRNAs significantly decreased the number of invadopodia per cell in these two cancer cell lines." (PMID 28912430, 2017). "For instance, an increase in Stim1 and Orai1 transcripts and proteins has been described in oestrogen receptor-negative human breast cancer cell lines, while TRPC1 up-regulation in these cells is still controversial." (PMID 24603752, 2014). "An increase in Orai1, but not Stim1, levels has also been reported in several breast cancer cell (BCC) lines, while the loss of Stim1 protein prevents SOCE activation in Wilms tumor cells." (PMID 23049731, 2012). "Interestingly, it has recently been shown that STIM1 regulates breast cancer cell migration through NFAT1 signaling independent of Orai1 and SOCE in breast cancer cells." (PMID 38505262, 2024). "Moreover, in luminal non-aggressive MCF7 breast cancer cells, miR-223 and miR-150 decline the expression of STIM1, but the impact of this regulation on breast cancer remains unexplored." (PMID 37932320, 2023). "Interestingly, the ability of TG to induce apoptosis in breast cancer cells expressing STIM1-YFP was significantly smaller than that observed in non-tumoral cells." (PMID 36612199, 2022). "Thus, in triple negative breast cancer cells, such as MDA-MB-231 cells, SOCE has been reported to be strongly dependent on STIM1 and Orai1, with TRPC6 playing a relevant role in the surface expression of Orai1, while in luminal breast cancer cells SOCE is mostly mediated by STIM1, STIM2, and Orai3." (PMID 33916304, 2021).